TAS2R7 (taste 2 receptor member 7)
Description:
Gustducin-coupled receptor implicated in the perception of bitter compounds in the oral cavity and the gastrointestinal tract. Signals through PLCB2 and the calcium-regulated cation channel TRPM5.
Synonyms: T2R7; TRB4
Tractability: Antibody: its Gene Ontology location is reachable by antibodies, with high confidence; UniProt predicts a signal peptide or a membrane-spanning region. PROTAC: a small molecule that binds it is known.
Target class: Membrane receptor; Taste receptor (taste family GPCR); Taste family G protein-coupled receptor
Gene: Protein-coding gene on chromosome 12 (10,801,532 to 10,802,627, reverse strand). Ensembl gene ENSG00000121377.
Subcellular location: Membrane
Pathways (Reactome):
Signal Transduction: Class C/3 (Metabotropic glutamate/pheromone receptors); G alpha (i) signalling events
Sensory Perception: Sensory perception of sweet, bitter, and umami (glutamate) taste
Gene Ontology:
Molecular function: bitter taste receptor activity; protein binding; taste receptor activity; G protein-coupled receptor activity
Biological process: detection of chemical stimulus involved in sensory perception of bitter taste; G protein-coupled receptor signaling pathway; sensory perception of taste
Cellular component: membrane; plasma membrane
Genetic constraint (gnomAD): Missense variants: 394 observed, 375.58 expected, observed/expected ratio (o/e) 1.05, 90% interval 0.96 to 1.14. Synonymous variants: 152 observed, 143.85 expected, observed/expected ratio (o/e) 1.06, 90% interval 0.93 to 1.21.
Homologues: Orthologues: chimpanzee TAS2R7 (99% identical), macaque TAS2R7 (94% identical), dog TAS2R7 (75% identical), rabbit TAS2R7 (75% identical), guinea pig TAS2R7 (73% identical), pig TAS2R7 (72% identical), rat Tas2r130 (68% identical), mouse Tas2r130 (67% identical). Paralogues in human: TAS2R9 (48% identical), TAS2R8 (45% identical), TAS2R3 (41% identical), TAS2R42 (40% identical), TAS2R10 (38% identical), TAS2R13 (37% identical), TAS2R14 (37% identical), TAS2R31 (36% identical), TAS2R43 (36% identical), TAS2R46 (36% identical), TAS2R20 (36% identical), TAS2R30 (36% identical), and 11 more.
Diseases named in the same sentence as TAS2R7 in open-access papers:
TAS2R7 is named in the same sentence as 5 diseases in open-access papers, as found by Europe PMC text mining. Sharing a sentence is not in itself a finding about the gene and the disease.
TAS2R7 shares sentences with these, for which no sentence is quoted: Anosmia (1 paper); breast carcinoma (1); parathyroid adenoma (1); parathyroid hyperplasia (1); type 2 diabetes mellitus (1).